MYCN (MYCN proto-oncogene, bHLH transcription factor)
Diseases named in the same sentence as MYCN in open-access papers (continued):
Sharing a sentence is not in itself a finding about the gene and the disease.
cancer (continued). "Ectopic expression of MYCN in the neural crest of zebrafish also induced NB, which substantiated that the potential of MYCN to induce this type of cancer is conserved among species." (PMID 36551697, 2022). "For example, dual inhibitors of BRD4 and PLK1 that prevent both MYCN transcription and promote N-MYC degradation, respectively, were found to exhibit antitumor effects in preclinical pediatric cancer models." (PMID 35883689, 2022). "In fact, MYCN amplification leads to deep remodeling of the cancer cell, influencing its apoptosis resistance, its undifferentiated status, its metabolic landscape and immune evasion." (PMID 36139583, 2022). "The deregulation of MYCN (N-MYC), as well as of other MYC family oncogenes, is frequently associated with a poor prognosis in many types of cancer." (PMID 36038612, 2022). "We found higher levels of metabolites involved in the transsulfuration pathway and confirmed in cell lines there are high levels of cystathionine across different tissues of high MYCN-expressing cancers." (PMID 35174317, 2022). "It is known that MYCNOS lncRNA regulates the expression of MYCN by binding to its promoter and influencing cancer cell phenotype, but its role in the regulation of immune cells has not been indicated." (PMID 36294833, 2022). "The MYC family of oncoproteins, including MYC, MYCL and MYCN, are ‘super‐transcription factors’ that mediate transcription of many metabolic genes and govern cellular metabolism in cancer cells." (PMID 35908258, 2022). "The transcription regulator MYCN (p = 6.08E−08) was also differentially expressed and is primarily involved in cancer specific signaling." (PMID 36450776, 2022). "Direct MYCN targeting strategies were shown to have limited effect, thus indirectly targeting the oncogenic activation of MYCN transcription is an important therapeutic approach for MYCN-driven cancers." (PMID 35205815, 2022). "Mechanistic studies showed that SMAD9 bound to the MYCN promoter, partially regulated MYCN expression and further mediated the cancer cell cycle." (PMID 36539767, 2022). "ABCG2 contributes to chemoresistance through the efflux of anticancer drugs from cancer cells and MYCN was shown to be positive regulator of ABCG2." (PMID 35996085, 2022). "In this study, we chose pan-cancer data to construct a more comprehensive network to predict potential targets for MYCN in terms of overall relationships, and finally verified the effect of indispensable genes combined with specific-diseases." (PMID 33968733, 2021). "Histone deacetylase (HDAC) inhibitors are effective in MYCN-driven cancers, because of a unique need for HDAC recruitment by the MYCN oncogenic signal." (PMID 33658627, 2021). "Overall, this dataset shows an unprecedented variability of gene expression within MYCN-Amplified cell lines, which supports further investigation of cancer cell line models via single-cell sequencing." (PMID 33525507, 2021). "NB is one of the first cancers in which amplification of the MYCN proto-oncogene in the form of extrachromosomal circularization has been described." (PMID 34830942, 2021). "In NB and other cancers, MYCN and mTOR signaling have been shown to play key roles in cancer stem cells and contribute to relapse and drug-resistance." (PMID 34565342, 2021). "Nonetheless, MYCN-driven cancer cells treated with PARP inhibitors enter mitosis with damaged DNA and undergo mitotic catastrophe, suggesting that increasing oncogene-dependent RS is another mechanism contributing to lethality by PARP inhibitors." (PMID 34508175, 2021).
cancer (continued). "Overall, based on the survival analysis, cancer pathway and drug targets analysis of indispensable genes, it is clear that the indispensable genes have a significant role in the MYCN regulatory network." (PMID 33968733, 2021). "Based on our microarray data, we specifically considered two hallmarks of cancer; altered metabolism and cell migration in RB in response to MYCN downregulation." (PMID 34680394, 2021). "Interfering with such RS-response (RS-R) and DDR proved effective in inducing cancer cell death, in MYCN-driven tumors." (PMID 34508175, 2021). "JQ1 treatment has been shown to be effective in MYC- and MYCN-driven MB by targeting cancer dependency genes driven by super-enhancers." (PMID 34195095, 2021). "Although MYC inactivation is therapeutically effective in preclinical models, validated means to directly target MYCN in cancer patients are lagging behind." (PMID 34508175, 2021). "The MYCN cancer gene in the MYC family is a structurally and functionally similar fragment of MYC discovered by Schwab in 1983." (PMID 33968733, 2021). "MYCN is known to influence diverse aspects of the cancer cells, dysregulating a large network of intracellular pathways." (PMID 33718189, 2021). "PI3K-mTOR signaling-driven deregulation of protein synthesis is very common in NB and various other cancers that promote MYCN stabilization." (PMID 34565342, 2021). "HDAC inhibitors have demonstrated strong efficacy in pre-clinical models of MYC and MYCN-driven cancer." (PMID 33658627, 2021). "As altered metabolism is one of the hallmarks of cancers, we specifically screened for significantly downregulated genes involved in glucose metabolism upon MYCN knockdown." (PMID 34680394, 2021). "BET protein inhibitors have been shown to target MYC/MYCN transcription in several cancers, including NB, demonstrating their potential as preclinical anticancer agents." (PMID 34565342, 2021). "The MYC family of transcription factors, including c-MYC (MYC), MYCL and MYCN are amongst the most commonly altered genes in cancer, including paediatric cancers." (PMID 34195095, 2021). "To further investigate the biological significance of indispensable genes in the MYCN network, we perform survival analysis of indispensable genes base on the clinical data of The Cancer Genome Atlas (TCGA) included 32 different cancers with 10,967 samples." (PMID 33968733, 2021). "Approximately 70% of NB patients with MYCN amplification show loss of heterozygosity (LOH) at 1p36, a segmental chromosomal alteration common to different human cancers, especially the ones affecting the nervous system." (PMID 34884690, 2021). "In preclinical studies, inhibiting BET protein function has shown promise as a therapeutic strategy to target MYCN in NB and other cancers." (PMID 34565342, 2021). "In vitro studies have shown the functional interactions between a number of these ncRNAs and MYCN, the oncogene that has essential roles in the pathogenesis of this type of cancer." (PMID 33718173, 2021). "MYCN plays an important role in many diseases and cancers, in-depth understanding of the role of MYCN has a great significance and application prospect." (PMID 33968733, 2021). "Considering the MYCN restricted expression in embryogenesis and it is impact in cancer, N-Myc is a promising target." (PMID 33718189, 2021). "While MYC is commonly activated in many cancers, MYCN is also increasingly recognized as important oncogenic driver in a growing number of cancer entities." (PMID 34262099, 2021). "In NB, elevated LIN28B expression levels inhibits let-7 with consequent de-repression of MYCN that reinforces cancer cell proliferation, activating the feedback loops of the MYCN-LIN28B axis." (PMID 34771690, 2021). "Carcinoma genome-wide methylation screening revealed that methylation of CNR1 was correlated with MYCN amplification, and patients with low mRNA expression levels of CNR1 had a poor prognosis." (PMID 34745201, 2021).
cancer (continued). "The MYC-MAX protein-protein interaction is required for MYC binding to DNA and poses as a great potential target in MYC and MYCN-driven cancers." (PMID 33585252, 2020). "In addition, given the demonstrated oncogenic relevance of MYCN in many types of cancers, we expect that further characterization of this network in other cancer types may lead to the development of novel diagnostic and therapeutic approaches to a broad spectrum of cancers." (PMID 32087738, 2020). "Its three related genes, c-myc (MYC), l-myc (MYCL), and n-myc (MYCN), have been found to be involved in many human cancers, with the regulation of some signal pathways leading to carcinogenesis." (PMID 33142921, 2020). "The deregulation of the MYC family of oncogenes, including c-MYC, MYCN and MYCL occurs in many types of cancers, and is frequently associated with a poor prognosis." (PMID 33628735, 2020). "JQ1 shows good efficacy in multiple MYC cancers as well as MYCN overexpressed CNS tumors such as MBs and NBs." (PMID 33585252, 2020). "SEs were found to be associated with various oncogenic molecules including both c-MYC and MYCN; this makes them putative therapeutic targets for cancer therapy." (PMID 33628735, 2020). "This review discusses MYCN genetic alterations in different types of cancers, the structure and transcriptional function of MYCN and the strategies used to target MYCN indirectly." (PMID 33628735, 2020). "MYCN targeted therapy has been proposed as a new strategy for cancer treatment, and many effort has been made to develop direct and indirect MYCN inhibitors with potential clinical applications." (PMID 32660514, 2020). "Synthetic lethality or ‘oncogene addiction’ offers an attractive therapeutic strategy for MYCN-driven cancers." (PMID 33628735, 2020). "The MYC- and MYCN-transformed cone precursors’ sensitivity to MDM2 knockdown suggests that MDM2 upregulation is an important part of MYC- as well as MYCN-mediated cancer initiation." (PMID 33425720, 2020). "Being a potent cancer proliferation driver, MYCN amplification contributes to the highly proliferative, malignant nature of the IMR-32 NB cells, which HSP90 inhibition with 17-AAG sufficiently abrogated." (PMID 33569349, 2020). "Highly proliferating cancer cells are often addicted to glutamine and studies have shown that MYCN leads to an upregulation of glutaminolytic enzymes, while also selectively inducing apoptosis in glutamine depleted cells." (PMID 33585251, 2020). "Among the MYC family of oncoproteins, over-expression of MYCN is restricted in some cancers, including NB." (PMID 32085516, 2020). "Knockdown of KDM4B decreases NB cell proliferation in vitro and NB xenograft growth in vivo, which provides proof-of-concept for the potential therapeutic efficacy of inhibiting KDM4B to target oncogenic MYCN signaling in cancers." (PMID 33628735, 2020). "Among several cancer-related genomic alterations, MYCN gene amplification, leading to MYCN protein overexpression, has been found in about 20% to 25% of NB cases, and is associated with increasing disease severity, rapid progression and poor disease outcome." (PMID 32085516, 2020). "After translation, the stability and activity of N-MYC protein are tightly controlled by ubiquitination-dependent proteasome degradation that is a brake in the MYCN-driven cancers." (PMID 33614505, 2020). "In NB and other cancers, targeting these transcriptional components leads to selective downregulation of superenhancer-associated genes, such as MYC or MYCN, that are characterized by high transcription levels and rapid turnover of RNA." (PMID 33016930, 2020). "Taken together, these findings by Xia and colleagues reveal new insight into the features of SGOC metabolism in the progression of NB with MYCN amplification or cancers with highly activated SGOC metabolism." (PMID 32034121, 2020). "FOXM1 is a known master regulator of cancer metastasis, the expression of multiple stem cell genes, as well as MYCN and AURK." (PMID 31627186, 2019).
cancer (continued). "MYCN, as a classical transcription factor, played a pivotal role in tumorigenesis and cancer progression that has been extensively studied." (PMID 31396265, 2019). "As a result, MYCN regulated a variety of cancer-related biological processes such as apoptosis, angiogenesis, invasion, and metabolism." (PMID 31396265, 2019). "MYCN amplified cancer cells also depend on mitochondrial metabolism to supply Krebs Cycle intermediates and the high energy demands associated with MYCN induced proliferation." (PMID 31455317, 2019). "Recent studies have shown that CHK1i alone can inhibit the proliferation of certain cancers, including MYCN-amplified NB." (PMID 31362335, 2019). "let-7 miRNAs are important in regulating the cell cycle and maintaining cells’ differentiated state by targeting a wide range of genes with known roles in cancer biogenesis such as MYC/MYCN, RAS, CDK6, and HMGA2." (PMID 31616462, 2019). "MYCN amplification and overexpression has also been found in a further small subset of pediatric and adult cancers such as medulloblastoma, retinoblastoma, glioma, lung, pancreas, prostate and hematological cancers." (PMID 35582571, 2019). "Collectively, MYCN knockdown altered chromatin state in the enhancers in multiple manners and impacted functions related to tumorigenesis and cancer progression." (PMID 31396265, 2019). "MYCN oncogene, that shows amplification in many human cancers, has an important role as a regulator of critical cellular processes including proliferation, cell growth and differentiation." (PMID 29581853, 2018). "Observing the same copy number gains as found in the MYCN driven model system (and other MYC driven murine cancer model systems) is a strong indicator of the role of murine chromosome 3 gene dosage contribution to MYCN driven oncogenicity." (PMID 29492199, 2018). "As a key MYCN-regulated process, the metabolic program is a critical biological pathway in cancer and has been recently validated as a therapeutic target." (PMID 29445162, 2018). "Meanwhile, TF MYCN is a central regulator of multiple vital cellular processes, and it has been described as an oncogene in multiple cancer types." (PMID 30195757, 2018). "In line with this, we have now demonstrated that MRE11 is also required for an efficient RS control and for the survival of preclinical models of established MYCN-driven human cancer." (PMID 30166519, 2018). "A relatively high frequency of overexpression of MYC was observed in kidney (48%) and colorectal (37%) cancers; of MYCL (variants 1 and 2) in uterine (58%) and breast (40%) cancers; and of MYCN in uterine (58%), liver (44%), and ovarian (43%) cancers." (PMID 28377632, 2017). "The comparison of all cancer cell lines versus HCK1T revealed that MYCN as well as MYC were activated, and the majority of the downstream genes were upregulated." (PMID 28261610, 2017). "The importance of MYCN in cell proliferation shows its potential to support the enhanced demand of cancers cells for increased cell growth." (PMID 28358317, 2017). "Recently, a number of whole-genome and whole-exome sequencing studies have broadened our understanding of the role MYCN amplification plays in this cancer." (PMID 28587062, 2017). "The strong inverse correlation suggests that MYCN amplification in cancer cells has a profound impact on host immune response to NB." (PMID 29163537, 2017). "Pharmacologic inhibition of MYCN oncoprotein is therefore of great interest in pediatric cancer; however, direct targeting of MYCN, or MYC oncoproteins in general, has not yet delivered viable therapeutics to the clinic." (PMID 27438153, 2016). "MYCN directly regulates the expression of NOXA in these cancers, with amplified MYCN leading to high expression of NOXA." (PMID 26859456, 2016).
cancer (continued). "This chemically driven screen appears to validate previous RNAi driven loss-of-function studies, which highlighted the potential for pharmacologic targeting of synthetic lethal interactions in MYCN expressing cancers." (PMID 27438153, 2016). "A previous study proposed that activated forms of the MYC and MYCN oncoproteins promote miR-9 expression via gene amplification in human cancers." (PMID 27612152, 2016). "Aberrant stimulation of MAPK or PI3K pathways also contributes to oncogenic stabilization of MYCN in certain cancers." (PMID 27438153, 2016). "Taken together with our study, TFAP4 appears to be initially upregulated by MYC or MYCN, after which it cooperatively regulates the same target genes to maximize rapid transcriptional activity in cancer cells." (PMID 27448979, 2016). "Genes from numerous cancer pathways were differentially expressed not only between MYCN single copy and MNA cell lines, but also between the patient-matched MNA lines KCN and KCNR." (PMID 26673823, 2015). "The possibility to specifically inhibit the function of both proteins is of great importance since it provides the bases to the design and development of novel therapeutic approaches to treat MYCN-induced cancers." (PMID 26062444, 2015). "This study implicated both known (KRAS, MYCN and TPD52) and novel (CCT6A, IGFBP3 and SALL2) cancer genes in TGCT pathogenesis." (PMID 25303610, 2015). "The MYC family of transcription factors consists of three well characterized members, c-MYC, L-MYC, and MYCN, deregulated in the majority of human cancers." (PMID 25477524, 2015). "Regions of high level gain or amplification encompassed key cancer genes such as MYCN (2p), the EVI1/MDS1 cluster (3q), FGFR1 (8p), OCT4 and MYC (8q) and KRAS (12p) of which a number are potential therapeutic targets." (PMID 26334103, 2015). "Effective pharmacologic targeting of the MYC family of transcription factor oncogenes, particularly targeting MYCN in pediatric cancer, has been a long sought after goal." (PMID 26029667, 2015). "In our EST database we see an overexpression of cellular retinoic acid binding protein 2 (CRABP2) together with MYCN proteins that have been shown to be upregulated and correlated in variety of cancers." (PMID 25243088, 2014). "Despite pediatric cancers bearing activation of MYCN are extremely malignant, their dependence on this oncoprotein for proliferation and survival makes them potentially curable diseases when more efficient ways of gene targeting will be developed." (PMID 26029658, 2014). "We thank Professor Akira Nakagawara, President of the Chiba Cancer Center, Japan, for kindly providing MYCN promoter luciferase reporters, as well as excellent research suggestions." (PMID 24586395, 2014). "In this network, many of the cancer-affected target mRNAs were mainly regulated by the transcription factors MYCN and FOXO1 which play a vital role in cell death, apoptosis, proliferation and survival." (PMID 21595958, 2011). "KEGG pathway analysis revealed a shortlist of genes whose promoters uniquely bound MYCN in the over expressing state and who are members of established signalling pathways which are dysregulated in cancer." (PMID 19997598, 2009). "MITF, which is not expressed in NB cells, has been shown to have a role in the regulation of melanocyte development and is similar to MYCN in that it is a reported oncogene which is amplified in cancer." (PMID 19997598, 2009). "The deregulation of MYCN occurs in many kinds of cancers and is related to poor prognosis." (PMID 41584037, 2026). "Notably, CD532 has undergone testing in multiple human cancer cell lines, revealing a robust association between sensitivity to CD532 and the presence of MYCN amplification and expression." (PMID 39802403, 2025).